GZMB (granzyme B)
Diseases named in the same sentence as GZMB in open-access papers (continued):
Sharing a sentence is not in itself a finding about the gene and the disease.
cancer (continued). "More recent studies suggest that the combination of granzyme B and the inflammatory cytokine TNF-α can activate this G2/M checkpoint, potentially reducing the susceptibility of these cancer cells to immune-mediated elimination." (PMID 40766321, 2025). "These immunotoxins, Rova-GrB (rovalpituzumab-granzyme B) and Rova-Typh (rovalpituzumab-typhoid), are designed to enter cancer cells and release toxins, namely, typhoid toxin and granzyme B, to induce cancer cell destruction." (PMID 40177519, 2025). "Inducing apoptotic cell death by granzyme B is crucial to eliminating threats, such as virus-infected or cancer cells." (PMID 40766321, 2025). "This culminated in the upregulated production of granzyme B, induction of apoptotic mechanisms, perhaps mediated by immune populations, through the activity of granzyme B and increased killing of cancer cells." (PMID 40429884, 2025). "This overexpression allows cancer cells to avoid destruction by the immune system by neutralizing the pro-apoptotic effects of GZMB." (PMID 40766321, 2025). "The expression of granzyme B, which is closely related to natural killer (NK) cell activity, can significantly affect the outcome of patients with these cancers." (PMID 40766321, 2025). "Overall, cytokines associated with effector lymphocyte cytotoxicity response (IFNg, perforin, granzyme A, granzyme B, and granulysin), cell death (FasL and TNFa), and IL-17A showed strong positive correlation with cancer cell killing (p = 0.025 to p < 0.0001)." (PMID 40589567, 2025). "Our observation of increased Granzyme B production suggests that HuTCR-T1 γδ T cells exhibit enhanced cytotoxicity against human cancer cells." (PMID 40801630, 2025). "CD8+ T cells, which function as CTLs, are critical for targeting and destroying cancer cells by inducing apoptosis through granzyme B and perforin." (PMID 40606756, 2025). "Granzyme B (GZMB) is a key cytotoxic element of the immune system, playing a fundamental role in killing cancer cells by inducing apoptosis." (PMID 40766321, 2025). "Perforin is crucial for the internalization of granzyme B into target cancer cells, allowing it to effectively induce the apoptosis cascade." (PMID 40766321, 2025). "Taken together, these results suggest that CD4+ T28zT2 T cells eliminated cancer cells mainly through secreting Granzyme B and IFN-γ." (PMID 40107245, 2025). "Future research should focus on further exploring the mechanisms of action of granzyme B and its role in cancer immunotherapy." (PMID 40766321, 2025). "The mean number of TIA-1-positive cells was similar to that of Granzyme B-positive cells in carcinomas." (PMID 40589751, 2025). "Granzyme B expression in carcinoma samples varied from few (below 5) to massive (over 40) per high-power field." (PMID 40589751, 2025). "Human pDCs are also endowed with direct effector functions via the upregulation of TRAIL and production of granzyme B, the latter modulated by cytokines abundant in cancer tissues." (PMID 39020402, 2024). "For example, rapamycin, an mTOR complex inhibitor, is regarded as an anti-cancer drug, yet it has been shown to downregulate GzmB expression in ILC1." (PMID 38745765, 2024). "Hou and co-workers found that flavonoids derived from Hippophae rhamnoides had the ability to increase the cytotoxicity of NK cells against K562 cancer cells by perforin/granzyme B production." (PMID 39619199, 2024). "In this regard, the delivery of cytotoxic proteins, such as granzyme B (GrB) and lysozyme, has emerged as a promising approach in cancer treatment." (PMID 39166136, 2024). "Vδ1 cells possess potent cytotoxic activity towards cancer cells in vitro and a high expression of cytotoxic effector proteins, such as Granzyme B." (PMID 38953978, 2024). "Bcl2 and Bcl-XL inhibit the loss of mitochondrial membrane potential mediated by Granzyme B, Bcl-XL, and BNIP3, as well as caspase-mediated apoptosis, thereby promoting cancer cell survival." (PMID 39518013, 2024).
cancer (continued). "It was also reported that NK cells turn cancer cells to death directly via perforin and granzyme B, which endorses them to be a valuable tool in cancer treatment." (PMID 39493763, 2024). "GZMB plays a key role in the immune system, and studies have shown that it participates in regulating cancer cell apoptosis during COAD immune responses, indicating its potential application in immunotherapy." (PMID 39850875, 2024). "Induction of soluble IFNγ and granzyme B by cancer cells were observed in culture supernatants and KO cells induced a marginal enhancement, as compared to the control cells." (PMID 38678024, 2024). "Further studies are warranted to delineate the relevant mechanisms and design GzmB-targeting strategies that improve combinatory cancer treatments." (PMID 38846935, 2024). "Perforin and granzyme B are expressed and secreted by immune cells, such as cytotoxic T cells and natural killer (NK) cells, to activate cancer cell death." (PMID 39375538, 2024). "It is also necessary to develop panels containing MDSCs markers as well as other markers like CD19 (B cells), Granzyme B (activated T cells), Foxp3 (regulatory T cells), α-SMA (cancer associated fibroblasts, CAFs) and FAP (CAFs) to characterize the TME." (PMID 38877529, 2024). "As a measure of CD8+ T cell function, we analyzed a potent cytotoxic molecule GzmB, which is present in cytotoxic granules and released upon contact with cancer cells to kill them." (PMID 38783281, 2024). "For instance, granzyme B, a serine protease secreted from natural killer cells and cytotoxic T cells, is involved in eradicating cancer cells." (PMID 37344563, 2023). "In several hypoxic tumors with high levels of autophagy, cancer cells counteract the degranulation of NK cells by regulating granzyme B degradation." (PMID 38071322, 2023). "For example, the top 15 hub genes in T cells from all types of cancers included those involved in cell-mediated immunity (GZMB, PRF1 and IFNG) and immune checkpoint signaling pathways (TIGIT and CTLA4)." (PMID 36350625, 2023). "CD4 + memory T cells can release some anti-tumor molecules such as IFN-γ, TNF-α, and Granzyme B. Therefore, a high frequency of these cells in the TME is associated with better survival of patients with cancer." (PMID 37221555, 2023). "Exposure to cell-free ascites supernatants from HGSOC patients drastically suppressed TAGLN2, IFNG, and GZMB expression in pre-activated CD8+ T cells obtained from peripheral blood of cancer-free women." (PMID 38168227, 2023). "This smart probe was successfully used to monitor GzmB activity in three different syngeneic mouse models of cancer and also in a model of pulmonary inflammation." (PMID 37376918, 2023). "Once TCRs of T cells bind antigens on cancer cells, T cells can kill cancer cells by releasing perforin and granzyme B." (PMID 37122741, 2023). "The differential expression of granzyme B was validated using conventional immunohistochemistry and was correlated to the cancer-specific patient survival." (PMID 37894418, 2023). "In general, NK cells produce perforin (Prf1) and granzyme B (GzmB) and induces cancer cell apoptosis." (PMID 37568788, 2023). "Both NK cells and CD8 + T lymphocytes can kill cancer cells by releasing some enzymes such as Granzyme B and perforin." (PMID 37221555, 2023). "The result of the current study therefore reinforces a cancer immunity role for GZMB in MSI, TMB high or PD-L1 high tumors." (PMID 37553332, 2023). "In IPA analysis, the top five enriched pathways included IL-15 production, circadian rhythm, Granzyme B Signaling, PD-1, PD-L1 cancer immunotherapy pathway and IGF-1 signaling." (PMID 38082307, 2023). "Immunohistochemical examinations of colon tissues showed significantly lower neutrophil counts, more granzyme B-positive but fewer MMP9 (gelatinase B)-positive cancer cells and lower numbers of apoptotic cells in mice receiving AAT therapy." (PMID 37532996, 2023).
cancer (continued). "Disruption of intercellular communication or low expression of Cx43-GJs has been shown to strongly inhibit granzyme B activity and Ca2+ influx, as well as NK cell-mediated cancer cell death." (PMID 36797782, 2023). "It is important to point out that the number of Granzyme B-positive-cancer and inflammatory cells in colon tissue increased upon AAT therapy." (PMID 37532996, 2023). "CD107a, granzyme B and IFNγ have been reported as effector function markers for the cytolytic activity of γδ T cells and other cytotoxic immune cells when encountering cancer cells." (PMID 37835538, 2023). "Increased Cx43-GJ cell-to-cell communication was observed in cytotoxic immune synapses (IS) formed between NK cells and cancer cells, allowing Ca2+ to flow into the cancer cells and promoting granzyme B activity and cancer cell apoptosis." (PMID 36797782, 2023). "The NK cells exhibit important roles in the suppression of cancer cells mediated by the perforin-granzyme B signaling pathway." (PMID 37958581, 2023). "The polarization of the cancer cell’s actin cytoskeleton provides robust protection against CL-mediated killing by efficiently reducing intracellular granzyme B levels within target cells." (PMID 37869010, 2023). "In contrast, expression of GZMB (granzyme B, a serine protease stored in activated T and NK cells that induces cancer cell apoptosis) and IFNG (activates cytotoxic T cells) were significantly higher in tumors with MSI-H, TMB ≥ 10 mutations/mb and PD-L1 ≥ 1%." (PMID 37553332, 2023). "Other important biomarkers involve the secretion of proteolytic enzymes (e.g., GzmA and GzmB), which are key effector molecules in cytotoxic T cells and can be used for real-time monitoring of anti-cancer immunotherapy efficacy." (PMID 37376918, 2023). "During neoplastic transformation, NK cells act by eliminating cancer cells from primary tumors and from metastatic sites through direct cancer cell lysis by secretion of granzyme B (GrzmB) and inflammatory cytokines." (PMID 37949944, 2023). "Since CD8+ T cells are recognized as the main effector cells of cell immunity which kill cancer cells by releasing perforin, granzyme B and IFN-γ." (PMID 38093288, 2023). "One of the most significantly upregulated proteins was granzyme B, which plays an important role in anti-cancer immune responses." (PMID 37894418, 2023). "Multivariate modelling showed that the fractions of proliferating CD8+TCF1+T cells and MHCII+ cancer cells were dominant predictors of response, followed by cancer–immune interactions with B cells and granzyme B+ T cells." (PMID 37674077, 2023). "It is well known that cytotoxic T cells depend on interferon gamma (IFN-γ) and granzyme B to attack cancer cells." (PMID 36816023, 2023). "In B2M-deficient cancers, γδ T cells showed frequent intraepithelial localization and expression of CD103 (tissue-residency), CD39 (activation), granzyme B (cytotoxicity) and Ki-67 (proliferation), as well as PD-1, consistent with the scRNA-seq data." (PMID 36631610, 2023). "In specific, TIS is referred to as an 18‐gene signature (CCL5, GZMK, CD3D, CD3E, CD2, HLA‐DRA, IL2RG, NKG7, CIITA, CXCR6, LAG3, TAGAP, HLA‐E, CXCL13, IDO1, CXCL10, STAT1, and GZMB), which was related to the response to ICIs in various cancers." (PMID 37434432, 2023). "Evidence indicates that ischemic cells preferentially activate phagocytosis to destroy the proapoptotic protein GzmB, which prevents the NK system from destroying cancer cells." (PMID 36816977, 2023). "Production of perforin and Granzyme B is essential for effector CD8+ T-cell cytotoxic activity against cancer cells." (PMID 37205112, 2023). "Studies have shown that NK EVs contain perforin, granzyme A, granzyme B, granulysin, and FasL, proteins that activate both intrinsic and extrinsic apoptosis pathways in cancer cells." (PMID 37818374, 2023).
cancer (continued). "Two major apoptosis pathways are necessary for regulating cell death in cancers: the intrinsic pathway, involving perforin and granzyme B, and the extrinsic pathway, involving FasL and TRAIL." (PMID 36068970, 2022). "Another approach has been co-treatment with small molecule immunomodulatory drugs that activate NK cells and increase granzyme-B expression or that increase the expression of NK activating ligands on cancer cells." (PMID 35874677, 2022). "Quantitative flow cytometric analysis also confirmed that the fluorescence signal of the probe H5 in cancer cells preceded that of Sytox Blue, which corroborates active GzmB as an early biomarker of immune-mediated cancer cell death." (PMID 35501326, 2022). "As a result, inflammatory factors attract natural killer cells and CD8+ T cells to the tumor site and directly eliminate cancer cells, with NK cells able to release granzyme B to further induce pyroptosis." (PMID 36612023, 2022). "As TCEs force the interaction between cancer cells and T cells, leading to release of granzyme B and perforin to activate caspases, we also stained for cleaved Caspase-3." (PMID 36405739, 2022). "One way to monitor the function of cytotoxic T cells in response to cancer immunotherapy is by imaging granzyme B, which is a serine protease that is secreted by both cytotoxic T cells and natural killer cells to induce cancer cell death." (PMID 36297474, 2022). "GZMB has been found to be expressed in urothelial, melanoma and pancreatic cells, which is thought to contribute to cancer invasion." (PMID 36497244, 2022). "Combining oncolytic viruses with TCEs provides an additional mechanism of cancer cell death, mediated by perforin and granzyme B release from T cells, and creates a bystander killing effect in the TME." (PMID 36405739, 2022). "One study found that cancer cells develop resistance to granzyme B/TNFα-mediated cytotoxic T cell killing by activating the G2/M cell cycle checkpoint." (PMID 36276148, 2022). "The chemical design of activity-sensing reporters of granzyme B (GzmB) represents a potentially effective strategy for monitoring the cytotoxic activity of CD8+ T cells in cancer." (PMID 35501326, 2022). "Cancer regrowth was associated with decreases in CD8 + T cells and NK cells and loss of granzyme B and IFN-gamma production, confirming the attenuation of inflammation." (PMID 35628540, 2022). "The analysis by ELISA of the CIK-conditioned medium, always collected at the end of 72 h cancer cell killing assays (n = 6), confirmed an intense production of protease granzyme B along with IFNα and IFNγ." (PMID 36142281, 2022). "Concurrently, the expression of higher levels of key cytotoxic pathway molecules granzyme B/perforin was induced, suggesting a greater cytotoxic potential for future application in adoptive cancer therapy." (PMID 36180901, 2022). "WEE1 overexpression abrogates immune cell killing, for example by protecting cancer cells from granzyme B/TNFα induced cell death." (PMID 36276148, 2022). "Given the importance of CD8+ T cells as effectors for eliminating cancer cells, we evaluated the co-expression of IFNγ and GZMb in CD8+ TILs—two commonly used markers to indicate their activation status and antitumoral activities." (PMID 35347124, 2022). "Expression of MLL3 or MLL4 is also negatively associated with GZMA, GZMB, and IFNG mRNA levels in a variety of human cancer types, highlighting increased immune cytotoxicity towards MLL3- and MLL4-low tumors." (PMID 36323669, 2022). "It has been shown that cancer cells can resist NK cell-mediated killing by decreasing granzyme B levels via autophagy, more specifically via activation of ULK1." (PMID 35203256, 2022). "We found tofacitinib suppressed IL-15-mediated JAK/STAT pathway stimulation, cytotoxicity to cancer cells and iNeurons, granzyme B and perforin expression, and cytokine expression in the NK-92 cell line." (PMID 35197969, 2022).
cancer (continued). "After several contacts between CD8+ T cells and cancer cells, the green fluorescence signal of H5 colocalized with the blue signal of Sytox Blue, indicating that targeted cancer cells had undergone GzmB-mediated apoptosis." (PMID 35501326, 2022). "Some studies demonstrated a correlation between GNLY and GZMB expressions and clinical outcomes in patients with several cancers." (PMID 35265561, 2022). "It has been suggested that Th9 cells initiate or incite a destructive program through secretion of granzyme B and other factors to cancer cells." (PMID 36241625, 2022). "If there are no additional signals to help regulate the production or secretion of GzmB, then this can lead to detrimental effects in chronic inflammatory diseases such as cancer." (PMID 35326588, 2022). "Granzyme B is able to induce apoptosis in cancer cell or cells infected with viral or bacterial pathogens via stimulating apoptosis." (PMID 36342273, 2022). "GzmB is a serine protease that is stored inactive in T cells until antigen-driven recognition prompts its release and activation inside cancer cells." (PMID 35501326, 2022). "ACT-dependent induction of granzyme B indirectly induced apoptosis of pancreatic, liver and breast cancer cells." (PMID 36700235, 2022). "This increase was accompanied by an accumulation of GZMB RNA expression and granzyme B protein, which directly mediates cancer cell cytolytic killing by CTL cells, in patient biopsy samples." (PMID 36923305, 2022). "In this review, we have summarized data that focus on the specific cellular production and regulation of GzmB, some promoting cancer growth." (PMID 35326588, 2022). "The increased cytotoxic gene expression (upregulated Prf1 and GzmB) in T cells found in chemo-sensitive tumors further substantiates the increased anti-cancer activity of IL-17A+ DOX sensitive tumors." (PMID 35924165, 2022). "Given the reactivity and selectivity of probe H5 for GzmB, we studied its utility to measure the cytotoxic activity of T cells during the attack on cancer cells." (PMID 35501326, 2022). "When NK cells are activated, CD56 and CD107a markers are able to recognize cancer cells and release perforin and granzyme B proteins that induce apoptosis in the targeted cells." (PMID 33440866, 2021). "Hypoxia activates autophagy to degrade the proapoptotic protein GZMB, thus inhibiting NK-mediated killing of cancer cells." (PMID 34484235, 2021). "In additionto biomarkers that are overexpressed in cancer cells,recent efforts have focused on evaluating biomarkers that can reportthe immune response against cancer, like the serine protease granzymeB (GzmB)." (PMID 34315210, 2021). "Specific delivery of GzmB in cancer cells has been achieved, for instance, by genetic fusion with an antibody moiety or a derivative of natural ligands binding surface cell proteins or receptors." (PMID 34529743, 2021). "Secretion of the pore-forming molecule Perforin-1 and proapoptotic protease Granzyme B, which can lead to granule exocytosis of cancer cells, was induced by the administration of rSmeg-hMIF-hIL-7." (PMID 34389619, 2021). "Our probe reacts with active granzyme B, a serine protease that NK cells deploy into cancer cells to induce apoptosis." (PMID 33300671, 2021). "GZMB expression on the other hand correlated well with these signatures in all cancers except for CRC CMS2, confirming this phenomenon to be CRC CMS2-specific." (PMID 34972191, 2021). "NK cells need to form IS with cancer cells to inject cytotoxic mediators, such as perforin and granzyme B, into cancer cells to induce apoptosis." (PMID 33816252, 2021). "Our observation of lower IFN-γ and granzyme B expression in high-thermogenesis TNBC along with lower CYT is consistent with these known findings showing lower anti-cancer activity of CD8+ T cells in TNBC with high thermogenesis, and, hence, thermal stress." (PMID 34071012, 2021).